SMAD4 (SMAD family member 4)
Diseases named in the same sentence as SMAD4 in open-access papers (continued):
Sharing a sentence is not in itself a finding about the gene and the disease.
tumor (continued). "However, in Smad4-negative cancer cells, KLF5 is not downregulated by TGF-β, and KLF5 and Sox4 cooperate to support tumor-initiating cells, thereby facilitating tumor progression." (PMID 38569937, 2024). "In agreement with our previous reports but contradicting a report by another group where a trend towards accelerated experimental metastasis in BMP4-treated mice was observed, in 231-HM and 4T1.2 tumors that expressed SMAD4, enforced BMP4 expression did not alter tumor growth kinetics." (PMID 38689334, 2024). "Furthermore, the VMT captures drug responses dependent on tumor-stroma interactions, as seen by the effectiveness of the TGF-βR1 inhibitor galunisertib on SMAD4 mutant SW480 VMT growth, a result that is not seen in monolayer or spheroid cultures." (PMID 36481562, 2023). "Knockout of SMAD4 by PDX1-Cre or P48 did not trigger cancer in mice, but it could facilitate tumor progression due to activation of KRASG12D or inactivation of PTEN." (PMID 32781778, 2020). "Immunohistochemistry showed that the expression of SMAD4 in PDAC carcinoma tissue was significantly lower than that in normal pancreatic tissue, and negative SMAD4 expression was closely related to tumour diameter, staging, lymph node metastasis and differentiation." (PMID 31684910, 2019). "While the parental HPDE cell line does not form tumours after orthotopic transplantation, expression of oncogenic KRASG12V and ERBB2 combined with short hairpin RNA-mediated knockdown of CDKN2A and SMAD4 produced lesions resembling invasive PDA after transplantation." (PMID 28272465, 2017). "On the other hand, SMAD4 haploinsufficient KPDC mice (SMAD4(+/−)) lacked RUNX3 expression, had a significantly lower metastatic burden, but showed an increased proliferative activity of the primary tumor compared to KPC tumors." (PMID 29100342, 2017). "However, SMAD4 re-expression in BxPC3 PCCs fails to suppress angiogenesis in vivo, and blocking TGF-β signaling suppresses tumor growth, metastasis, and angiogenesis in orthotopic mouse models." (PMID 26586478, 2016). "Notably, negative or positive correlation between HPSE and Smad4 or LEF1 expression was observed in different NB and neuroblastic tumor cohorts." (PMID 27595937, 2016). "However, we also observed a trend towards longer survival times in Smad4-negative patients, indicating the complex role of TGF-β signaling in tumor progression." (PMID 16438724, 2006). "In the absence of SMAD4, the TGF-β signalling pathway-mediated downregulation of NLE1 is prevented by the ectopic expression of c-MYC, which occupies the E-box-containing region within the NLE1 promoter and upregulates NLE1, thereby promoting tumour progression." (PMID 37685308, 2023). "Furthermore, when DCs were incubated with culture medium supernatant of tumor cells, the percentage of CD80+ cells also increased by supernatant from Smad4KO but not WT PDAC cells, nor Smad4&StingKO cells, indicating the essential role of tumor‐intrinsic STING‐mediated signaling in DC activation." (PMID 35064757, 2022). "Before injection of PACO2 SMAD4-GFP cells, FACS analysis revealed that ∼97% of the cells were positive for the expression of the transgenic construct, and it is likely that the negative fraction of modified cell populations induced the tumor engraftment in a few mice." (PMID 32420409, 2020).
tumor (continued). "Besides, the integration of the SMAD4-PΨg in the SCAI gene has been corroborated in hereditary cancer-predisposition cases, and while SCAI is characterized to have suppressive effect on tumor cell invasiveness, it has not been determined whether SCAI expression is hindered by the SMAD4-PΨg." (PMID 35114952, 2022).
cancer (789 papers, 1998 to 2026). A tumor composed of atypical neoplastic, often pleomorphic cells that invade other tissues. "To address these gaps, we conducted an oncogenic PPI (OncoPPI) profiling to systematically identify previously unreported physical interactions between SMAD4 and cancer-associated proteins." (PMID 40856537, 2026). "In SMAD4-deficient cancer cells, disruption of this interaction liberates NFATc1, enabling activation of oncogenic pathways such as STAT3 signaling." (PMID 40856537, 2026). "Cancer genomic studies have identified the SMAD4 gene as one of the most frequently mutated genes across multiple malignancies, including pancreatic, colon, and lung cancers." (PMID 40856537, 2026). "Further we also identify key master cancer regulators like SMAD4, EP300, KAT6A and TAF1 which are associated with multiple cancers and are related to critical oncogenic processes." (PMID 41404623, 2025). "Its expression is modulated by cancer-associated fibroblasts (CAFs) through the TGF-β/SMAD4 signaling pathway, which promotes aggressive cancer phenotypes." (PMID 40724877, 2025). "The majority of SMAD4 loss of function (LOF) cancer somatic mutations are missense, although nonsense, splice site, frameshift, and in-frame insertion/deletion mutations exist." (PMID 40348815, 2025). "Our platform’s versatility was validated through the correction of additional cancer-associated mutations in SMAD4, PTEN, and KRAS, demonstrating its broader applicability in dissecting the functional roles of diverse genetic alterations." (PMID 40696461, 2025). "For instance, miRNAs such as the miR-17-92 cluster and miR-26a have been implicated in regulating components of the SMAD4/C-MYC/Cyclin D1 axis in other cancer types." (PMID 40224178, 2025). "SMAD4 inactivation through mutations or deletion makes it an attractive molecular marker in cancer pathogenesis." (PMID 40338154, 2025). "TGF-β ligands suppress growth yet can paradoxically and potently promote cancer invasion and metastasis depending on downstream pathway mutational context, such as loss of Mothers against decapentaplegic homolog 4 (Smad4)." (PMID 40348815, 2025). "Subsequently, we investigated the PPI and PDI signals using cell lysates expressing SMAD4 R361H and R361C, two naturally occurring cancer-associated hotspot mutations in the MH2 domain that are known to impair the SMAD4–SMAD3 PPI." (PMID 37968137, 2024). "Next-generation sequencing (NGS) analysis using a panel of 25 hereditary cancer-related genes performed on the index case’s DNA identified a heterozygous variant in SMAD4 intron 2 (NM_005359.6: c.424+5G>A), which was confirmed by Sanger sequencing." (PMID 39063183, 2024). "The signaling activation leads to Smad4-mediated cell death or survival, cancer suppression, and restoration of memory loss in AD, depending upon the strength of signal activation." (PMID 38542478, 2024). "Only SMAD4 showed lower expression in cancer tissues and was simultaneously associated with poor prognosis." (PMID 38914552, 2024). "Dysregulation of SMAD4 is associated with various aspects of cancer progression, encompassing autophagy, invasion and metastasis, underscoring its significance in cellular responses and disease." (PMID 38666907, 2024). "The literature review carried out in this study revealed that 12 unique SMAD4 splicing variants have been reported to date in 24 patients with cancer and/or JPS." (PMID 39063183, 2024). "In this study, we found that DLG1 was significantly downregulated in PDAC cancer tissues with SMAD4 loss." (PMID 38789418, 2024). "This study expands the landscape of SMAD4 germline genetic variants associated with GI polyposis and/or cancer." (PMID 39063183, 2024).
cancer (continued). "In PDAC, CAF-derived thrombospondin 1 (TSP1) activates TGF-β signaling, leading to the loss of Smad4 expression in cancer cells and accelerating their proliferation and migration." (PMID 39534084, 2024). "Carcinogenesis in the large intestine can lead to the loss of tumor suppressor genes, such as APC and SMAD4, which normally prevent cancer development." (PMID 38674816, 2024). "Applying this cut-off value in our case series, 85 cases were defined as SMAD4 loss cancers out of the 245 EAC cases from the entire EACSGE consortium (35%)." (PMID 36900206, 2023). "Mutations in the SMAD2, SMAD3, and SMAD4 genes are associated with cancers of the intestine, pancreas, or appendix." (PMID 37509254, 2023). "Studies have shown that higher levels of SMAD1, SMAD2, and SMAD4 expression are associated with good overall survival (OS) in stage I and II cancer." (PMID 37685308, 2023). "SMAD4 expression was inversely related to age, explaining why SMAD4 deficiency commonly occurs in the elderly and why cancers tend to occur in senile people." (PMID 37035326, 2023). "SMAD4 genetic alterations, either via genomic loss or via mutations, can be found in many cancer types." (PMID 37377893, 2023). "Second, loss of SMAD4 induces cancer cell dedifferentiationandpromotes cancer stem cell (CSC) development." (PMID 36450103, 2023). "Several studies revealed the correlations between mutations of SMAD family proteins (Smad2, Smad3, Smad4 and Smad7) and various diseases and cancers, with the intracellular signal transduction molecule proteins (SMAD) in the TGF-β pathway." (PMID 37742025, 2023). "The Smad4/Tgfβ pathway is mutated in 60% of all CRCs and is most often associated with late-stage cancer progression, poor prognosis, and cancer invasion." (PMID 38136364, 2023). "Patients with SMAD4-negative cancers exhibit a two-fold greater risk of recurrence and three-fold higher risk of mortality than those with SMAD4-positive cancers." (PMID 38003265, 2023). "The role of SMAD4 in intestinal homeostasis has been further reported in genetic mouse models, in which SMAD4 deficiency in T cells drove chronic inflammation and cancer." (PMID 35426367, 2022). "It is considered that the inactivation of SMAD4 is remarkably associated with the invasiveness of cancer." (PMID 36081557, 2022). "These subclones harbored putative metastasis-driving mutations in cancer-related genes such as SMAD4, ROBO1, and DICER1." (PMID 36476508, 2022). "Genes in the TGF-beta signaling pathway, including SMAD4, were more frequently mutated in i3 cancers." (PMID 35773407, 2022). "Higher mutated frequency in Wnt signalling of pancreatic body/tail cancers mainly resulted from distinctly enriched SMAD4 mutations (P = 0.008), and more abundant LRP1/1B and CTNNB1 mutations." (PMID 33452856, 2021). "An association has been established between KRT23 and Smad4 in malignant cells, promoting Smad4-dependent upregulation and subsequent migration of cancer cells." (PMID 34885040, 2021). "Comprehensive analysis of a large number of samples allowed us to define a profile of SMAD4 mutations in most common human cancers covered by TCGA." (PMID 33406242, 2021). "On the other hand, the loss of Smad4 (a transducer of TGF-β signaling) promotes cancer progression and induces EMT." (PMID 34163033, 2021). "This is the first study that used meta-analysis approach to prove that SMAD4 expression loss indeed promoted the cancers drug-resistance significantly." (PMID 34048444, 2021). "The result indicated that SMAD4 expression loss correlation with the drug resistance was independent on the cancer type." (PMID 34048444, 2021).
cancer (continued). "Since metastasis and recurrence were also correlated to cancer resistance, we also pooled the RRs (risk ratio) of metastasis and recurrence in SMAD4 subpopulation to evaluate the effect of SMAD4 expression loss on chemoresistance." (PMID 34048444, 2021). "Through alterations in the mechanisms of TGF-β signaling, for instance, disabling mutations in TβRII and Smad4, cancer cells develop tolerance to the tumor-suppressive effects of TGF-β in advanced stages of cancer." (PMID 34947978, 2021). "Loss of Smad4 plays a causal role in facilitating the initiation and development of varieties of cancers, such as colorectal carcinoma, squamous cell cancer, and pancreatic cancer." (PMID 33372356, 2021). "Although our findings proved that SMAD4 loss rendered the cancer cells resistance to chemotherapy, however, there are still some limitations in this study." (PMID 34048444, 2021). "The pooled HR (95% CI) was calculated to be 1.23 (1.01–1.45), indicating that the loss of SMAD4 expression in the cancers resulted in chemoresistance." (PMID 34048444, 2021). "The homozygous deletion or inactivating mutations of SMAD4 play a crucial role in the malignant progression of certain cancer types." (PMID 34070531, 2021). "Here, we aim to evaluate the association between SMAD4 expression and the drug resistance in cancers by performing a meta-analysis." (PMID 34048444, 2021). "In humans, genetic variants in the SMAD4 have been found to play a protective role in various types of cancers." (PMID 34413874, 2021). "The HR of each subgroup was >1 and p <0.01, which means SMAD4 expression loss significantly promoted cancer resistance independent on the antibody brand." (PMID 34048444, 2021). "Two cancer-associated mutations of SMAD4 enhance phosphorylation of SMAD4 by GSK3β, which promotes its degradation and thus loss of function." (PMID 33918004, 2021). "SMAD4, located on chromosome 18, a key conveyer of TGFβ signaling and found to be mutated in several types of cancer has been suggested to be haploinsufficient in mouse models." (PMID 33509126, 2021). "Our data are consistent with previous studies and indicate that loss of Smad4 promotes cancer development and progression." (PMID 33372356, 2021). "The HRs and risk ratios (RRs) with 95% confidence intervals (CIs) were used to explore the association between SMAD4 expression losses with drug resistance in cancers." (PMID 34048444, 2021). "KRAS G12S is a hotspot oncogenic gain-of-function mutation, whereas the biological effect of SMAD4 P356L is unclear, although this mutation is recurrent in various cancers and is predicted to be oncogenic." (PMID 35008475, 2021). "The results of PPI demonstrated that the five TFs were tightly associated with many critical cancer related factors or pathways, such as SMAD4, MMP13, IL-5, IL-2, CYP2E1, CCNE1 and CDH1." (PMID 34405021, 2021). "In cancer tissues, 14 mutations were detected in the coding regions and intronic region of the SMAD4 gene." (PMID 35154600, 2021). "Inactivating mutations in SMAD4 are far more common in PDAC (31%) than in other cancer types, and are generally associated with high-grade PanIN lesions." (PMID 35008235, 2021). "Secondly, TGFβ can actively exert its oncogenic effect in Smad4-deficient cancers through stabilizing ID1 protein." (PMID 33990575, 2021). "The EAC in this study did not include any submucosal invasive cancer, and it is possible that EAC in this study was early cancers before SMAD4 is mutated." (PMID 34480065, 2021). "In the clinical studies, most of the reports showed that SMAD4 loss was correlated with cancer malignancy and prognosis." (PMID 34048444, 2021). "Our findings are consistent with other reports that negative regulation of SMAD4 expression by other miRNAs is associated with suppressed cell motility and invasiveness in different cancers 31-34." (PMID 33746597, 2021).